ERBB2 (erb-b2 receptor tyrosine kinase 2)
Diseases named in the same sentence as ERBB2 in open-access papers (continued):
Sharing a sentence is not in itself a finding about the gene and the disease.
melanoma (342 papers, 2001 to 2026). A malignant, usually aggressive tumor composed of atypical, neoplastic melanocytes. "We demonstrated that ACA-28 has a unique property to induce ERK-dependent apoptosis in melanoma cell lines (with either BRAF or NRAS mutation) as well as NIH/3T3 cells harboring mutationally active HER2/ErbB2." (PMID 38500550, 2024). "Exome sequencing of a kindred with a familial cancer syndrome characterized by both MPN and melanoma produced a germline variant in the ERBB2/HER2 gene that co-segregates with disease." (PMID 34209587, 2021). "ERBB2 expression was associated with melanoma lesions with a Breslow depth of <2 mm." (PMID 35915735, 2022). "ERBB2 mutations were found in cutaneous (1%), acral (2%), and mucosal (2%) melanomas." (PMID 35915735, 2022). "Interestingly, the germline variants identified in this study are located throughout the ERBB2 protein, but they notably spare the KD and ECD hotspot regions, similar to germline ERBB2 variants reported in breast, lung, melanoma, and pediatric cancers." (PMID 34209587, 2021). "Further studies are needed to clarify the role of ERBB2 mutations in melanoma, as it may help for considering targeted therapy." (PMID 30181807, 2018). "Indeed, lapatinib, a clinical ERBB2 and EGFR inhibitor, effectively inhibited the ERBB3/ERBB2 pathway and importantly, delayed melanoma tumor growth in both mutated and wild type BRAF cells." (PMID 28060735, 2017). "To investigate the impact of the treatments on key signaling pathways involved in melanoma progression, we evaluated the expression and activation status of ERBB2, BRAF, PI3K, AKT1, and mTOR by immunofluorescence analysis." (PMID 40806647, 2025). "Other significantly reduced proteins include TRAIL, TGFR-2, ANXA1, SPARC, FURIN, GPNMB, and ERBB2, all of which play roles in melanoma progression, immune modulation, or resistance to targeted therapies." (PMID 40725203, 2025). "This case presents a promising novel therapeutic strategy for ERBB2-amplified cervical mucosal malignant melanoma, highlighting the value of molecular subtyping in guiding off-label therapies." (PMID 40969261, 2025). "Our findings demonstrate that hydroxytyrosol effectively reprograms the tumor microenvironment in 3D melanoma spheroids by downregulating the ERBB2/3/4 axis and suppressing key oncogenic pathways such as PI3K-Akt and MAPK/ERK." (PMID 40725203, 2025). "Both compounds exhibited favorable binding energies with several targets, including PI3K, AKT1, mTOR, BRAF, and ERBB2, all of which are critical regulators of cell proliferation and survival in melanoma." (PMID 40806647, 2025). "This case report is the first to document significant clinical benefit achieved with the combination of toripalimab and T-DXd, in a patient with ERBB2-amplified cervical mucosal malignant melanoma." (PMID 40969261, 2025). "While HFF-1 showed higher levels of EGFR (p = 0.001) and JAK-3 (p = 0.001) genes compared to MeWo, the melanoma cell line presented higher expression of ERBB2 (p = 0.001), and ITK (p = 0.04)." (PMID 38790974, 2024). "Future studies are warranted to test neratinib reversal of BRAFi/MEKi resistance in patient melanomas expressing ERBB3/HER3 in combination with its dimerization partner ERBB2/HER2." (PMID 38854737, 2024). "This interaction relationship can be the basis for subsequent studies on the mechanism of drug resistance in melanoma with ERBB2 as the entry point." (PMID 35915735, 2022). "The protein expression of ERBB2 was higher in melanomas compared to the melanocytes in normal skin tissue." (PMID 35915735, 2022). "As an essential factor in regulating cell death, ERBB2 plays a critical role in the occurrence of melanoma drug resistance." (PMID 35915735, 2022). "In melanoma, ERBB2 was detected by antibody CAB000043 with low staining, moderate-intensity and <25% quantity." (PMID 35915735, 2022).
melanoma (continued). "Sdc1 in chronic wounds autoactivates ErbB2, which is a characteristic of melanoma, suggesting that as wounds become chronic, they show many characteristics of cancer." (PMID 36009225, 2022). "We need more studies on the relationship between ERBB2 and melanoma resistance and developing it into medicine in the future." (PMID 35915735, 2022). "Our MS analysis identified the growth factor receptor HER2/ERBB2 as a constituent enriched in MVs derived from melanoma cells with supernumerary centrosomes and increased MT growth rates." (PMID 36875714, 2022). "Other targeted drugs have not been thoroughly studied and supported in the treatment of melanoma, such as the classic target gene-ERBB2 of breast cancer." (PMID 35915735, 2022). "We have identified a rare heterozygous germline ERBB2 missense variant that co-segregates with disease in a familial cancer syndrome manifesting as MPN, melanoma, and other solid tumors." (PMID 34209587, 2021). "FAN1 was the most common germline mutation gene in our cohort, of which 27 variations were found, followed by the genes EGFR, ERBB2, and MSH3, which were found mutated 20 times in melanomas of our study." (PMID 32083130, 2020). "NVP-BEP800 induced degradation of several melanoma oncoproteins including ERBB2, CRAF, BRAFV600E and AKT." (PMID 31659567, 2020). "off the coast of Brazil were reported to have potent anticancer activity against a leukemic and melanoma cell line, and the active compound, prodigiosin, was shown to be selective for cancers overexpressing ErbB-2." (PMID 31221160, 2019). "HSi substantially reduced ErbB2 protein levels in several types of human tumor cell lines, including those of breast, ovarian, and melanoma origins." (PMID 31617560, 2019). "Here we show that melanoma tumor growth is inhibited by 60% over controls when treated with lapatinib, a clinically approved inhibitor of ERBB2/EGFR." (PMID 28060735, 2017). "Gained therapies included tyrosine kinase inhibitors (TKIs) in the context of EGFR-mutated NSCLC, trastuzumab deruxtecan for ERBB2-mutated NSCLC, ivosidenib for IDH1-mutated CCA, MEK and RAF inhibitor combination therapies for BRAF V600E melanomas, and PARP inhibitors for BRCA2-mutated HGSOC." (PMID 40399445, 2025). "Furthermore, we demonstrated that differential expression of all investigated Ibrutinib target genes (i.e., BTK, EGFR, ERBB2, ITK, JAK3, and TEC) is associated with apoptotic mechanisms in clinical melanoma samples." (PMID 38790974, 2024). "In 732 melanoma cases, ERBB2 amplifications were detected in acral (3%) and mucosal (3%) melanomas." (PMID 35915735, 2022). "Through machine learning, our study proves that ERBB2-targeted drugs may play an important role in treating drug-resistant melanoma." (PMID 35915735, 2022). "After we identified ERBB2 as the promising target of drug-resistant melanoma by DeepPurpose." (PMID 35915735, 2022). "The abnormal expression of the ERBB2 gene had been studied in melanoma." (PMID 35915735, 2022). "However, the research on the role of ERBB2 in melanoma is still insufficient, especially on the mechanism of drug resistance." (PMID 35915735, 2022). "Moreover, the ERBB2/ERBB3 complex seems to be a promising target for combination tumor therapy in cutaneous melanoma, and activated NOTCH1 and ERBB2/ERBB3 signaling are involved in melanoma pathogenesis, supporting our data." (PMID 33786987, 2021). "In recent study no ERBB2 mutations were found in melanoma, however the importance of ERBB2 mutations in the kinase domain is well documented in a wide variety of human cancers." (PMID 30181807, 2018). "Thus, in melanoma, one sample (6.2%) had an uncommon BRAF (c.1400C>T; p.Ser467Leu) mutation, one (6.2%) had an NRAS (c.385C>T; p.Gln129*) mutation, and rare EGFR, ERBB2, KRAS, and MET mutations were also exhibited in one sample (6.2%)." (PMID 28404952, 2017).
melanoma (continued). "Interestingly, we have recently shown that PI3K/AKT and NFκB are major survival pathways downstream ERBB3/2 in melanoma; and that lapatinib effectively inhibits ERBB2 and ERBB3 activation." (PMID 28060735, 2017). "Dysregulation of the PI3K-AKT-mTOR pathway, either through amplifications (i.e. ERBB2), deletions (i.e. PTEN), or as a direct result of mutations (i.e. PI3KCA), has been closely linked to the development, progression and chemoresistance of melanoma." (PMID 26204252, 2015). "Interestingly, the increased erbB3 in melanoma or thyroid cancers also depended upon erbB2 to activate the downstream signaling Akt or MAPK." (PMID 24886126, 2014). "In conclusion, abnormal expression of ERBB2 was associated with the development of melanoma and might be independent of the canonical driver." (PMID 35915735, 2022). "In melanoma and fibrosarcoma, overexpression of EGFR and ERBB2 sensitizes tumors to ferroptosis-inducing treatments through activation of the RAS/RAF/c-Myc/ACSL4 signaling axis." (PMID 40846695, 2025). "By intersecting the key cluster and the intersection of drug-related genes and melanoma-related genes, we finally identified three crucial targets, EGFR, ERBB2, and CDK2, which are all protein serine/threonine kinases and are involved in cell cycle regulation." (PMID 38348352, 2023). "We previously demonstrated that melanoma relies on the activation of ERBB signaling, specifically of the ERBB3/ERBB2 cascade." (PMID 28060735, 2017). "Our results reveal that hydroxytyrosol selectively disrupts key oncogenic pathways, including ERBB2/3/4, PI3K-Akt, and MAPK signaling, providing new insights into its anti-melanoma potential and highlighting its utility as a candidate for adjunct therapy in melanoma." (PMID 40725203, 2025). "Our findings suggest that cinobufagin may affect melanoma by arresting the cell cycle by inhibiting three protein tyrosine/serine kinases (EGFR, ERBB2, and CDK2)." (PMID 38348352, 2023). "ERBB2 amplifications were detected in acral (7%) and mucosal (6%) melanoma among 140 patients without canonical driver alterations." (PMID 35915735, 2022). "ERBB2 CNG was also seen in patients with anal cancer, carcinoma unknown primary, cervical cancer, melanoma, neuroendocrine cancer, renal cell carcinoma, and salivary gland cancer (n = 1 for each)." (PMID 35126865, 2022). "Melanoma progression depends on activation of ERBB signaling, especially the ERBB3/ERBB2 cascade." (PMID 33732282, 2021). "This suggests it may be possible to treat ErbB4-dependent melanomas using anti-EGFR and -ErbB2 therapies, particularly small molecule EGFR and/or ErbB2 tyrosine kinase inhibitors." (PMID 33378376, 2020). "Additionally, the ERBB family members EGFR, ERBB1, ERBB2 and ERBB3 are known to be involved in driving several oncogenic processes in melanoma." (PMID 28223541, 2017). "Similarly, in melanoma, we have demonstrated that ERBB3/ERBB2 is a key survival signaling unit that acts mostly by activating AKT." (PMID 28060735, 2017). "ATA displayed higher growth inhibition ability on breast cancer especially ErbB-2/HER2/Neu positive cancer cells than normal cells and it inhibited MDA-MB-435 (now a confirmed melanoma cell line) xenograft growth in mice at a dose of 30 mg per kg by i.p. injection, three times per week." (PMID 23202971, 2012). "We have recently shown that up to 70% of melanomas, regardless of whether they possess mutated or wild type BRAF, show hyper-activation of ERBB3 and rely on an ERBB3/ERBB2 signaling cascade to promote cell survival." (PMID 28060735, 2017). "Additionally, we find that while ERBB3 and ERBB2 are affected by the treatment, EGFR was not, further reiterating our previous results that an ERBB3/ERBB2 signaling cascade operates in melanoma and is mostly responsible of the activation of PI3K/AKT signaling." (PMID 28060735, 2017).
melanoma (continued). "Development of just a single ERBB3 peptide vaccine can be found in the literature however, peptide vaccines targeting ERBB1, ERBB2 or both ERBB1/2 including monoclonal antibody against tyrosine related protein 1 (TRP-1) and altered peptide sequence to gp100 for mouse melanoma all show promise." (PMID 28591206, 2017). "The colony morphology induced by LL-37 was strikingly similar to the growth pattern reported for a melanoma cell line exposed to EGF-like peptides, and for mammary epithelial cells overexpressing ERBB2, which was hypothesised to mirror an increased metastatic potential." (PMID 19183447, 2009). "In this regard, EGFR, PTEN, ESR1, FGFR2 and ERBB2 were more frequently detected in CSF ctDNA than in blood in a cohort of NSCLC and BC as well as in patients with melanoma and negative CSF cytology." (PMID 34207653, 2021). "In most patients, melanoma cells exhibited ErbB3/Her3, CD44/Pgp-1, ICAM-1/CD54 and IGF-1-R/CD221, but did not express CD20, ErbB2/Her2, KIT/CD117, AC133/CD133 or MDR-1/CD243." (PMID 24489649, 2014). "Using melanoma cell lines lacking or expressing FLNA, Fiori and collaborators have shown that this protein is an important regulator of EGFR members (including ERBB2) that ensure efficient ligand-mediated activation of these receptors and, consequently, intracellular trafficking and degradation." (PMID 21210970, 2010).
pancreatic cancer (319 papers, 2003 to 2026). "The aim of this article is to analyze the tissue expression of EGFR, Beta catenin, cyclin D1, CDK4, and ErbB2 in pancreatic cancer in order to find their association with the mortality and survival of patients with this tumor." (PMID 35448172, 2022). "Conversely, claimed the relevance of ErbB2 as an independent prognostic factor in patients with pancreatic cancer, associated with poorer outcomes." (PMID 35448172, 2022). "ERBB2, or HER2, is a receptor tyrosine kinase, and its overexpression is associated with poor prognosis in pancreatic cancer." (PMID 35154607, 2021). "Using NGS to detect mutations, and then ddPCR for further analysis, mutations in ERBB2 (either in exon 17 or 27) have been detected in the ctDNA of 20% of pancreatic cancer patients." (PMID 31608239, 2019). "ErbB2 targeted therapies, using antibodies or catalytic inhibitors, remain poorly efficient in pancreatic cancer, and have also been associated with ill side effects in other cancers." (PMID 31723153, 2019). "HER2, also known as ERBB2, is a receptor tyrosine kinase, and overexpression of HER2 is associated with poor clinical outcomes in pancreatic cancer." (PMID 29670173, 2018). "Our results show for the first time that the loss of ErbB2 sensitizes pancreatic cancer cells to gemcitabine treatment." (PMID 25890497, 2015). "The loss of ErbB2 in CAPAN-2 pancreatic cancer cells induces an increase of SN-38 chemoresistance." (PMID 25890497, 2015). "ERBB2, a receptor tyrosine kinase, is overexpressed in a subset of pancreatic cancers and a predictive tool for survival in patients with pancreatic cancer in histological studies." (PMID 40952239, 2025). "In a study sequencing 336 pancreatic cancer specimens, potentially actionable targets were identified in 26% of cases, including alterations in ERBB2, BRCA1 or BRCA2, BRAFV600E, ROS1, and ALK1." (PMID 40227779, 2025). "Though ErbB2 is involved in pancreatic inflammation and oncogenesis, NF-κB/miR-488/ErbB2 axis is reported to modulate pancreatic tumor growth." (PMID 38533139, 2024). "In this path, ErbB1 (epidermal growth factor receptor/EGFR) and especially ErbB2 (HER2/neu) are more important in pancreatic cancer." (PMID 38559560, 2024). "Patients with pancreatic cancer had a considerably higher expression of the ErbB2 gene than patients with CP." (PMID 38533139, 2024). "We describe two cases of ERBB2-amplified pancreatic cancer patients treated with anti-HER2 therapy and provide data on the frequency of ERBB2 amplifications and KRAS alterations identified by clinical circulating cell-free DNA testing." (PMID 38406801, 2024). "The pancreatic cancer cell cycle, viability, and apoptosis of the disease are all impacted by NF-κB transcriptionally inhibiting ErbB2 expression, as demonstrated by data from Chinese patients with PC." (PMID 38533139, 2024). "Patients with pancreatic cancer and chronic pancreatitis often have overexpressed tyrosine kinase receptors, like ErbB2 of the epidermal growth factor receptor family." (PMID 38533139, 2024). "In patients with IHC 1–2+ tumors, a positive association with ERBB2 copy number was seen in UBC, but the relationship was less evident in pancreatic cancer and cholangiocarcinoma." (PMID 37119523, 2023). "Patients with KRAS wild‐type disease and early‐onset pancreatic cancer (EOPC) harbored actionable mutations including BRAF, EGFR, ERBB2, and MAP2K1/2." (PMID 36999792, 2023). "Patients with KRAS wild‐type disease and early‐onset pancreatic cancer (EOPC) harbored actionable mutations including BRAF, EGFR, ERBB2, and MAP2K1/2.PGVs in PALB2, BRCA2, and ATM were associated with high PDAC risk in the Chinese population." (PMID 36999792, 2023).